LINC02835 (long independently transcribed non-coding RNA 2835)
Synonyms: lncMER52A
Gene: Long non-coding RNA gene on chromosome 4 (65,206,455 to 65,241,817, reverse strand). Ensembl gene ENSG00000285711.
Diseases named in the same sentence as LINC02835 in open-access papers:
LINC02835 is named in the same sentence as 3 diseases in open-access papers, as found by Europe PMC text mining. Sharing a sentence is not in itself a finding about the gene and the disease.
LINC02835 shares sentences with these, for which no sentence is quoted: hepatocellular carcinoma (1 paper); liver cancer (1); tumour (1).